FOXP3 (forkhead box P3)
Diseases named in the same sentence as FOXP3 in open-access papers (continued):
Sharing a sentence is not in itself a finding about the gene and the disease.
Autoimmunity (continued). "The complex network that regulates Treg cell plasticity, including cooperative/counteractive transcription factors, external cues, and the stable transcription of Foxp3, represents a great promise for future treatment of several immune-related diseases, including autoimmunity and cancer." (PMID 32117202, 2019). "Tregs are characterized by the expression of CD4, CD25 and the transcription factor forkhead box P3 (Foxp3), and are known to exert immunosuppressive effects, which can be beneficial in preventing overt autoimmunity, but can hamper the development of antitumor immune responses." (PMID 30756132, 2019). "In this context, it has been shown that defects in IL-2/IL-2R signaling in Treg cells profoundly contribute to the development of autoimmunity since IL-2 has a key role in the control of Foxp3 expression in CD4+CD25+ cells, through the phosphorylation of STAT3 and STAT5 proteins." (PMID 32117202, 2019). "The full comprehension of inflammation-induced mechanisms controlling Foxp3 expression and Treg cell plasticity could be useful for the identification of new molecular targets to control autoimmunity or immunodeficiency." (PMID 32117202, 2019). "The dysregulation of Foxp3 long intergenic non-coding RNA (FLICR) can decrease FoxP3 levels and; therefore, T regulatory cells (Treg) control, leading to autoimmunity, showing that lncRNA controls both pro- and anti-inflammatory processes, as next described for infectious diseases." (PMID 30781588, 2019). "Here the authors show that O-GlcNAcylation of Foxp3 and Stat5, mediated by O-GlcNAc transferase (OGT), is essential for Treg-mediate immune balance, with Treg-specific deficiency of OGT leading to severe autoimmunity." (PMID 30664665, 2019). "Since the maintenance of a stable and functional pool of Treg cells is crucial to ensure proper immune tolerance and homeostasis, it is relevant to deeply understand the epigenetic mechanisms and factors that stabilize Foxp3, on which the balance between tolerance and autoimmunity depends." (PMID 32117202, 2019). "Thus, failure of these CD4+ Foxp3+ T cells to suppress autoimmunity in CD25cKO mice cannot be attributed to their absence in the periphery, but is instead consistent with a lack of suppressive function." (PMID 30833563, 2019). "Overall, data presented in this study indicates that CD8+HLA-DR+ Treg and CD4+FOXP3+ Treg share phenotypic and functional features, and that they may be similarly involved in the control of antitumor immune responses and autoimmunity." (PMID 30555473, 2018). "We and others have demonstrated that mice lacking EZH2 in natural FOXP3+ Tregs developed spontaneous multi-organ inflammation and were more susceptible to experimental models of autoimmunity." (PMID 30619315, 2018). "EZH2 is required to promote the FOXP3-mediated gene repression program following TCR stimulation.Loss of EZH2 in Tregs in vivo leads to multi-organ inflammation and increases susceptibility to experimental models of autoimmunity." (PMID 30619315, 2018). "Pro-inflammatory T helper (Th) 17 cells are required for the pathogenesis of MS and its mouse model, the experimental autoimmune encephalomyelitis (EAE), whereas CD4+Foxp3+ regulatory T cells (Treg), crucial for preventing autoimmunity, are defective in numbers and functions." (PMID 30671056, 2018). "Overall, the data presented in this study indicate that CD8+HLA-DR+ Treg and CD4+FOXP3+ Treg share phenotypic and functional features, which may provide cues to similar involvements in the control of antitumor immune responses and autoimmunity." (PMID 30555473, 2018). "We propose that a better understanding of the activation-dependent, adenosine-related functional conversion of γδ T cells could lead to γδ T cell-targeted immunotherapies in autoimmunity and other conditions affected by Foxp3+ regulatory T cells." (PMID 29771938, 2018).
Autoimmunity (continued). "The clearest link between FOXP3+ Tregs and autoimmunity comes from the disorder immunodysregulation polyendocrinopathy enteropathy X-linked syndrome (IPEX), in which there are loss-of-function mutations in the FOXP3 gene." (PMID 28770318, 2017). "Furthermore, in IL-2−/− or CD25−/− mice, the expression of FOXP3 in thymocytes was drastically reduced and these animals developed fatal autoimmunity disorders." (PMID 28589115, 2017). "Intriguingly, Foxp3+CD4 regulatory T cells may represent a path toward developing antigen-specific tolerance in both autoimmunity and transplant recognition." (PMID 29259578, 2017). "In parallel, the regulation of cognition-promoting autoimmunity exerted by Foxp3 might have been scaled by species-specific features of the Foxp3 gene." (PMID 29123465, 2017). "Foxp3+ Treg cells are known to promote immunological tolerance and suppress autoimmunity." (PMID 28485401, 2017). "Notably, in autoimmune disorders CD4+/CD25+/FoxP3+ dependent suppression of effector cells (macrophages, natural killer, dendritic, and cytotoxic T cells) was reported." (PMID 28902871, 2017). "We have previously shown that the CD4-driven fatal autoimmunity seen in Foxp3-deficient mice is abrogated in the absence of OX40 and CD30, whereas CD8 immunity was preserved." (PMID 28646041, 2017). "One long-term goal of the islet transplantation and autoimmunity field is to either deplete “indirect” autoreactive CD4 T cells or re-educate these CD4 T cells to become Foxp3+ regulatory CD4 T cells, while also generating additional “indirect” Tregs specific for transplant-derived antigens." (PMID 29259578, 2017). "While rebound Tregs are dysfunctional, DT-resistant Foxp3+ Tregs have been shown to protect against lethal autoimmunity and may thus suffice to control the SR CD4+ T cells during chronic JHMV infection." (PMID 27708643, 2016). "Specific Foxp3+Treg induction in the context of autoimmunity could allow modulating the immune response for clinical benefit while limiting long-term immune suppression." (PMID 26975663, 2016). "The essential function of human Foxp3+Tregs to avoid autoimmunity is illustrated by the fatal autoimmune disease IPEX (immunodysregulation, polyendocrinopathy, enteropathy and X-linked syndrome), which is caused by mutations in the Foxp3 gene." (PMID 26975663, 2016). "FOXP3 is a master regulator of the development and function of Treg cells, which play an essential role in preventing autoimmunity by contributing to the maintenance of immunological self-tolerance and immune homeostasis, and whose number and/or function is altered in RA." (PMID 27834806, 2016). "In addition we examined the expression of FOXP3, the key transcription factor of Treg cells, which help to constrain autoreactive T cells and prevent autoimmunity." (PMID 27386265, 2016). "Foxp3 acts in conjunction with specific changes in DNA-methylation to drive full commitment to the TReg identity Lack or loss of functional Foxp3 leads to widespread autoimmunity caused by the absence of TReg cells." (PMID 26107960, 2015). "Therefore, exploring the molecular mechanisms behind the function of the Treg cell-lineage transcription factor FOXP3 in autoimmunity would provide insight into the understanding of the stability and plasticity of Treg cells." (PMID 26441996, 2015). "Characterizing the FOXP3+ T cell populations could have a high impact in monitoring and treating many diseases, including those diseases with autoimmunity, cancer, and allergy." (PMID 26500760, 2015). "In addition to these effector subsets, the CD4+ Treg, characterized by the forkhead box P3 (Foxp3) protein, suppresses adaptive T-cell responses and prevents autoimmunity." (PMID 25689696, 2015). "Therefore, further studies are needed to better clarify the identity and role of CD4+Foxp3+CD25− cell population in autoimmunity." (PMID 26592184, 2015).
Autoimmunity (continued). "Mice with Foxp3+ Treg cells deficient in IL-10 do not develop severe autoimmunity but do develop spontaneous gastrointestinal inflammation." (PMID 25606598, 2014). "In this paper, we provide an overview of currently available mouse models to study the role of Foxp3+ Treg cells in the control of destructive β cell autoimmunity, including a novel NOD model that allows specific and temporally controlled deletion of Foxp3+ Treg cells." (PMID 23691523, 2013). "We observed an increase of miR-31 in splenocytes from murine lupus, which may contribute to autoimmunity by suppressing regulatory T cell (Treg) development or function as it was reported to target Foxp3, a lineage specific transcription factor for Tregs." (PMID 24175965, 2013). "T-bet expression is required for full Treg function, as T-bet deficient nTreg do not fully control autoimmunity in FoxP3 deficient scurfy mice." (PMID 23935597, 2013). "Overall, the RIP-HA model offers unique opportunities to study mechanisms of antigen-specific suppression of β cell autoimmunity, employing cotransfer of TCR-HA+ Treg cells, either with a Foxp3+ or Foxp3− phenotype, together with pathogenic T effector cells (CD4+TCR-HA+ or CD8+CL4+)." (PMID 23691523, 2013). "In addition to the elimination of self-reactive T cells, recent studies indicated roles of mTECs in the development of Foxp3-positive regulatory T cells, which suppress autoimmunity and excess immune reactions in peripheral tissues." (PMID 23986760, 2013). "CD4+CD25+Foxp3+ regulatory T cells (Tregs) are essential in the induction and maintenance of immune tolerance and therefore play a critical role in the prevention and inhibition of inflammation and autoimmunity." (PMID 23977081, 2013). "Foxp3+ regulatory T (Treg) cells are key immune regulators during helminth infections, and identifying the mechanisms governing their induction is of principal importance for the design of treatments for helminth infections, allergies and autoimmunity." (PMID 23319295, 2013). "Collectively, these studies indicate that during lymphopenia, Foxp3 deletion or autoimmunity, a fraction of TREG cells could acquire a pro-inflammatory IFNγ-secreting phenotype." (PMID 23345540, 2013). "Absence of CD4+CD25+FoxP3+ natural suppressor T cells has been shown to enhance the development of T cell-mediated autoimmunity, whereas adoptive transfer of these cells was associated with opposite effects." (PMID 22727044, 2012). "Loss of FoxP3 leads to functionally deficient TREG and causes fatal autoimmunity." (PMID 23118856, 2012). "Mutations in the FOXP3 gene (located on the centromeric region of the X chromosome) lead to decreased CD4 + CD25+ Tregs, and therefore failure to suppress the production of autoreactive T cells and multi-organ autoimmunity." (PMID 22816667, 2012). "CD4+CD25+Foxp3+ regulatory T (Treg) cells inhibit autoimmunity and protect against tissue injury." (PMID 22591709, 2012). "In addition to the important role of natural Foxp3+ Treg cells (nTreg) in preventing autoimmunity, it has become established that Foxp3 expression can be peripherally induced following T-cell activation in presence of TGF-β." (PMID 23056063, 2012). "In a similar set of experiments, miR-146a-deficient hematopoietic cells failed to rescue Foxp3-deficient T-cell-mediated autoimmunity." (PMID 22401860, 2012). "Consequently, CD4+Foxp3+ Tregs are gaining impetus as prophylactics or therapeutics in order to regulate various immune disorders such as transplant rejection, autoimmunity and allergy." (PMID 22957107, 2012). "When Foxp3+ Treg are depleted in an adult individual, fatal multiorgan autoimmunity finally results and the phenotype of this disease is virtually indistinguishable from genetic deficiency of Foxp3 that is characterized by a massive lymphoproliferative syndrome." (PMID 21234340, 2010).
Autoimmunity (continued). "Based on our observations in the autoimmunity and viral infection models, we hypothesized that systemic depletion of Foxp3 protein would selectively interfere with these tumor-associated TREG cells, while leaving TREG cells elsewhere in the body relatively unaffected." (PMID 40478934, 2025). "This presence of a regulatory transcriptome in cells that have lost their cognate master regulator has important implications for manipulating Treg cells in cancer and autoimmunity and may serve as an indicator of cellular identity independently of Foxp3 expression." (PMID 40568113, 2025). "Consequently, lower FOXP3 expression in Tregs after EV infection may impair the suppression of antiviral responses and tissue inflammation, contributing to autoimmunity." (PMID 39234544, 2024). "Analyses of peripheral blood populations in patients with 22q11.2DS have demonstrated decreased absolute numbers of FOXP3+ Treg, which has been hypothesized to contribute to the increased incidence of autoimmunity and allergies which affect a significant proportion of these patients." (PMID 37006241, 2023). "Foxp3-deficient mice exhibit lethal autoimmunity and lack of CD4+CD25+ cells." (PMID 36982782, 2023). "The importance of FOXP3, the Treg master transcription factor, is well illustrated by the clinical syndrome IPEX (immunopathology, polyendocrinopathy, enteropathy, X-linked) resulting from a loss-of-function FOXP3 mutation and causing often-fatal autoimmunity from an absent Treg compartment." (PMID 35960852, 2023). "Interestingly, FOXP3+ regulatory T cells (Tregs), which play a pivotal role in prevention of autoimmunity have been demonstrated to highly overexpress CSF2RB and genome-wide association studies (GWAS) identified CSF2RB as being linked to autoimmune diseases like multiple sclerosis (MS)." (PMID 36532080, 2022). "The circulating CD4+CXCR5+FOXP3+ Tfrs with enhanced suppressive function could alleviate autoimmunity in RA patients by reducing IgG and IgM levels, and the proportion of Tfrs was negatively correlated with the disease severity, which provided a novel insight into RA pathogenesis." (PMID 35474948, 2022). "Due to the strong decrease in Foxp3+ Treg population, the net suppressive capacity of the remaining Foxp3+ Treg cells might not be sufficient to protect the organism against development of autoimmunity." (PMID 35563702, 2022). "Thus, the resulting reduction in Foxp3 expression and corresponding reduction in suppressive Treg activity may promote autoimmune disorders." (PMID 35935991, 2022). "Forkhead box p3 (Foxp3) is the master regulatory transcription factor that shapes the fate of Treg cells, and its deficiency leads to an absence of Treg cells and induction of autoimmunity." (PMID 34222235, 2021). "The deletion of Helios specifically in Tregs also did not result in a rapid onset of autoimmunity, unlike Foxp3-deficient mice (Scurfy) but to an autoimmune-like syndrome with a lymphocytic infiltration of immune cells in nonlymphoid tissues and auto-Ab production appearing after five months." (PMID 33924428, 2021). "However, loss-of-function studies in non-autoimmune and diabetes-prone mice have not been able to demonstrate an unequivocal link between Foxp3+ Treg cell deficiency and catastrophic β cell autoimmunity." (PMID 34447385, 2021). "However, Zhang and colleagues reported that Eomes promotes the development of type 1 regulatory T (Tr1) cells, a Foxp3 negative regulatory T cell subset, which might have potent immunosuppressive functions in autoimmunity." (PMID 33390832, 2021). "It is tempting to speculate that a lower expression of FOXP3 in Treg cells after enterovirus infections might lead to impaired suppression of anti-viral responses and tissue inflammation, which could contribute to the induction of autoimmunity." (PMID 33643278, 2020).
Autoimmunity (continued). "Both FOXP3 and RORγt were undetectable in three patients with IL2RG, RAG1 and STAT1 mutations, implying that Treg and Th17 cells were almost completely absent, and therefore they had increased risks of developing autoimmune disorders and opportunistic infections." (PMID 32670274, 2020). "In this sense, the objective of the present study was to identify polymorphisms in important mediators of the immune response (FOXP3, IFNG, IL6, IL8, IL10, MBL2, CRP, TGFΒ1 and TNFA) in association with ANAs, which could contribute to the development of autoimmunity in hepatitis C." (PMID 32743104, 2020). "Acute course of fatal autoimmunity in mice and humans with congenital Foxp3 defects also implies that an abundance of autoreactive CD4+Foxp3− cells and diversity of their TCRs may need to be re-examined to better understand the pathogenesis of autoimmune diseases." (PMID 31653839, 2019). "Thus, these Foxp3+ regulatory T cells could further modulate the immune system and relieve the autoimmunity in vivo." (PMID 30760702, 2019). "Nevertheless, a rather intriguing finding in both of these settings, as in our model, is that receptor deficient mice did not develop autoimmunity, prompting the idea that Treg cells were set to a low IL-2 receptor signaling threshold sufficient for Foxp3 induction and maintenance." (PMID 30560927, 2018). "Therefore, the upregulation of Foxp3+ Tregs might be useful for suppressing the activation of autoimmune T cells and controlling autoimmune disorders." (PMID 28367355, 2017). "We showed that this strategy restores Treg function in T lymphocytes from patients carrying mutations in FOXP3 [immune-dysregulation, polyendocrinopathy, enteropathy, X-linked (IPEX)], in whom CD4FOXP3 T cell could be used as therapeutics to control autoimmunity." (PMID 29075264, 2017). "FoxP3, the master transcription factor of regulatory T cells (Tregs), plays a key role in Treg function, which is strongly related to the induction of tolerance against self-antigens (prevention of autoimmunity) and environmental allergens including food allergens (prevention of allergy)." (PMID 28933365, 2017). "However, in contrast to our study, previous study found that the absence of the Foxp3+ T cells causing autoimmunity in both humans and mice." (PMID 28542613, 2017). "Even though underlying mechanisms remain beyond the competence of this study, our findings warrant further research into FOXP3+T-bet+ T cell compartment in HT and may contain relevant investigation targets that will accelerate our understanding of Treg insufficiency in autoimmunity." (PMID 27478306, 2016). "Because of the excellent capacity of stem cell-derived Treg cells in suppression of autoimmunity, generation of antigen-specific Foxp3+ Treg cells from stem cells such as iPSCs and HSCs may open a new area in Treg cell-based immunotherapy in transplantation and autoimmune disorders." (PMID 25152867, 2014). "Moreover, we postulate that the rapid rebound of Tregs that occurs in mycobacteria-infected DEREG mice at the expense of a small population of DT-resistant FoxP3 cells may hamper the impact of Treg depletion on pathogen burden, while preventing autoimmunity." (PMID 25050936, 2014). "In any case, this striking difference to human IPEX patients regarding the manifestation of autoimmune diabetes limits the exploitation of mice with constitutive genetic Foxp3 deficiency and concomitant absence of functional Treg cells in studies on pancreatic β cell autoimmunity." (PMID 23691523, 2013). "Besides the correlation of B cell subsets, specifically switched memory B cells, with autoimmunity, there is evidence from multiple human and mouse models on the significance and importance of regulatory T cells expressing FOXP3 in suppressing or controlling autoimmunity." (PMID 22837758, 2012).